FBN1 (fibrillin 1)
Diseases named in the same sentence as FBN1 in open-access papers (continued):
Sharing a sentence is not in itself a finding about the gene and the disease.
FBN1 also shares sentences with these, for which no sentence is quoted: Ehlers-Danlos syndrome (9 papers); dissection (7); Weill-Marchesani syndrome 2 (6); Pectus excavatum (5); hepatocellular carcinoma (4); neurofibromatosis type 1 (4); arrhythmogenic right ventricular cardiomyopathy (3); hypertrophic cardiomyopathy (3); Marfan syndrome type 2 (3); melanoma (3); Myocardial fibrosis (3); Shprintzen-Goldberg syndrome (3); type 2 diabetes (3); acute myocardial infarction (2); aniridia (2); aortic insufficiency (2); autosomal dominant polycystic kidney disease (2); brachydactyly (2); Coronary artery dissection (2); craniosynostosis (2); dwarfism (2); familial hypercholesterolemia (2); familial thoracic aortic aneurysm (2); head and neck squamous cell carcinoma (2); heart failure (2); macular degeneration (2); Mitral regurgitation (2); nephrolithiasis (2); Noonan syndrome (2); osteogenesis imperfecta (2).
A further 164 diseases each share a sentence with FBN1 in 2 papers or fewer.